SLC27A4 (solute carrier family 27 member 4)
Diseases named in the same sentence as SLC27A4 in open-access papers (continued):
Sharing a sentence is not in itself a finding about the gene and the disease.
cancer (18 papers, 2018 to 2025). A tumor composed of atypical neoplastic, often pleomorphic cells that invade other tissues. "A high expression of SDHA and NUP210 were positively associated with the unfavorable prognosis of AML patients and an elevated expression of SLC27A4 was linked to poorer clinical outcomes in several cancer types." (PMID 38254953, 2023). "Among these, artificial intelligence highlighted SLC27A4 and LMNB1 as proteins that maximize the discrimination between cancer and non-cancer samples, with SLC27A4 associated with controls, and LMNB1 with MB samples." (PMID 36005596, 2022). "SLC27A4 has been proved to be dysregulated in cancers and is involved into the regulation of cancer progression." (PMID 32425696, 2020). "Fatty acid transporter proteins (CD36, Fabp1, Slc27a4) mediate the uptake of fatty acids and were reported to be highly expressed in cancer cells and to function in tumor growth." (PMID 32156004, 2020). "Arachidonic acid is also known as a fatty acid that links to cancer metastasis; on the other hand, palmitic acid and lignoceric acid (C24:0) are known substrates of SLC27A4." (PMID 30388870, 2018). "Studies on cancers revealed increased or decreased levels of SLC27A4 according to cancer type." (PMID 36556492, 2022). "Nonetheless, SLC27A4 may also be significant in the tumorigenesis of other cancers." (PMID 37239243, 2023). "Functionally, SLC27A4‐KD in PLC/PRF/5 and HLE cells impairs cancer properties, as indicated by reduced migration, invasion and colony formation abilities." (PMID 40237223, 2025). "The authors confirmed the downregulation of several genes in at least 7 cancer types, including ACOX3, PKC2, SLC27A4, and SLC27A2." (PMID 33562532, 2021). "Therefore, the biological networks of SLC27A4 were evaluated by TCSBN database, which provided biological networks in various types of cancer and non-cancer tissues." (PMID 30388870, 2018). "Currently, the interaction of SLC27A4 is not well-known in cancer cells." (PMID 30388870, 2018). "On the other hand, oleic acid (C18:1), which has antitumor effects in several types of cancers, is a preferred substrate of SLC27A1 and SLC27A6, but not SLC27A4." (PMID 36005596, 2022). "Regarding SLC27A4, no study has investigated its involvement in CRC, and available observations refer to other types of cancers." (PMID 36556492, 2022).
tumor (18 papers, 2013 to 2025). "Notably, SLC2A1, SLC25A29, and SLC27A4 were identified as key genes associated with survival and tumor stage." (PMID 37775731, 2023). "Analysis of TCGA dataset revealed that a significant number of HCC patients exhibited higher levels of SLC27A4 (n = 50) in tumorous tissues than in paired normal tissue samples." (PMID 40237223, 2025). "In agreement with the in vitro model, subcutaneous injection of PLC/PRF/5 SLC27A4‐KD cells into mice resulted in significantly slower tumour growth and reduced responsiveness to sEV from metastatic cells compared to CTL‐KD cells." (PMID 40237223, 2025). "The expression of SLC27A4 was lower in both males and females in the enhancing tumor region (in females p = 0.019; in males p = 0.004) and tumor core (in males p = 0.004) compared to the peritumoral area." (PMID 37239243, 2023). "However, in the enhancing tumor region and the tumor core, the expression of SLC27A4 was significantly lower compared to the peritumoral area (p = 0.0007 and p = 0.004, respectively)." (PMID 37239243, 2023). "The other tumor suppressor, such as wild type p16, might be important for regulating cell cycle in SLC27A4-silencing Hs578T." (PMID 30388870, 2018). "Collectively, these results emphasize the importance of SLC27A4 as a downstream activator of sEV‐NAMPT and its role in mediating tumour aggressiveness and glycolysis." (PMID 40237223, 2025). "For example, a positive correlation was found between SLC27A3 in the enhancing tumor region and SLC27A1 in the tumor core, and between SLC27A4 in the peritumoral area and SLC27A6 in the tumor core." (PMID 37239243, 2023). "Women also showed a negative correlation in the expression of SLC27A3 in the peritumoral area with the expression of SLC27A4, SLC27A5, and SLC27A6 in the enhancing tumor region." (PMID 37239243, 2023). "In women, a positive correlation was observed between the expression of ELOVL1 and SLC27A4, SLC27A5, and SLC27A6 in the tumor core." (PMID 37239243, 2023). "Positive correlations were observed between SLC27A4 and SLC27A5, SLC27A4 and SLC27A6, and SLC27A5 and SLC27A6 in all three tumor regions." (PMID 37239243, 2023). "The results showed that SLC27A1 and SLC27A3 were higher-expressed in tumor samples of both sets, while SLC27A2, SLC27A4, and SLC27A5 expressions were much lower." (PMID 35927229, 2022). "SLC27A4 was also overexpressed in lung tumor tissues and in triple negative breast cell lines (Hs578T and MDA-MB-231) with respect to non-tumor tissues." (PMID 36005596, 2022). "Negative correlations were observed between SLC27A3 and SLC27A4 in the enhancing tumor region and between SLC27A1 and SLC27A5 in the tumor core." (PMID 37239243, 2023). "A positive correlation was observed between the expression of SLC27A1 and SLC27A3 in the enhancing tumor region, while a negative correlation was found with the expression of SLC27A4, SLC27A5, and SLC27A6." (PMID 37239243, 2023). "Specifically, a positive correlation was found between SLC27A1 and SLC27A4 with age in the tumor core, while a negative correlation was found with SLC27A5." (PMID 37239243, 2023). "In the tumor core of women, there was a negative correlation between the expression of SLC27A5 and a positive correlation between the expression of SLC27A4 and SLC27A1 with age." (PMID 37239243, 2023). "In the tumor core, but not in the enhancing tumor region, there was a positive correlation between the expression of SLC27A1 and SLC27A4, both of which are involved in fatty acid uptake through the BBB." (PMID 37239243, 2023).
psychiatric disease (1 paper, 2025). "Our results also showed that many psychiatric disease-associated remarkable genes, were upregulated (SLC35F1, SNHG5, and FAM118A) or downregulated (SLC26A3, SLC27A4, LINGO1, and RASGEF1B) in PBMCs of patients with WD." (PMID 40384935, 2025).
SLC27A4 also shares sentences with these, for which no sentence is quoted: Insulin resistance (10 papers); dermopathy (5); autosomal recessive congenital ichthyosis (3); bladder cancer (3); metabolic disease (3); atopic dermatitis (2); cardiovascular diseases (2); Clear Cell Renal Cell Carcinoma (2); gestational diabetes (2); restrictive dermopathy (2); allergies (1); atherosclerosis (1); bladder tumor (1); bladder urothelial carcinoma (1); colon cancer (1); eosinophilia (1); facial paralysis (1); gastric cancer (1); Gaucher disease (1); Hepatic fibrosis (1); Hyperglycemia (1); Hyperkeratosis (1); infection (1); laryngeal carcinoma (1); Melkersson-Rosenthal syndrome (1); monocytic leukemia (1); morbid obesity (1); neurological disorders (1); nonalcoholic steatohepatitis (1); pustular psoriasis (1).
A further 5 diseases each share a sentence with SLC27A4 in 1 paper.